GPBAR1 (G protein-coupled bile acid receptor 1)
Diseases named in the same sentence as GPBAR1 in open-access papers (continued):
Sharing a sentence is not in itself a finding about the gene and the disease.
cholestasis (31 papers, 2015 to 2025). Impairment of the bile flow caused by obstruction within the liver, or outside the liver in the bile duct system. "If Ca2+-dependent HCO3− secretion is determined to play a necessary role in cholestasis, then InsP3R deficiency may affect the efficacy of GPBAR1 to some extent." (PMID 35095513, 2021). "BAR502, a bile acid analogue, is active as dual FXR/GPBAR1 agonist and represents a promising lead for the treatment of cholestasis and NASH." (PMID 39086986, 2024). "Mouse models of biliary fibrosis and cholestasis showed an increased cholangiocyte proliferation via the Gpbar1-mediated activation of the epidermal growth factor receptor and ERK pathway." (PMID 36899928, 2023). "Since GPBAR1 is also distributed in the intestine and GPBAR1 regulates cholestasis, is there a close relationship between GPBAR1 and the intestinal microbiota?" (PMID 35095513, 2021). "Since GPBAR1 is widely expressed in these enterohepatic circulation tissues, it tends to regulate cholestasis through a variety of different pathways." (PMID 35095513, 2021). "Considering the high expression of GPBAR1 in the intestine, GPBAR1 seems to be able to improve cholestasis by regulating intestinal inflammation." (PMID 35095513, 2021). "Some studies have suggested that BA-induced pruritus in cholestasis is associated with GPBAR1 receptor activation, suggesting a potential side effect of GPBAR1 in cholestasis treatment." (PMID 35095513, 2021). "In line with this possibility, GPBAR-1 KO mice exposed to partial hepatectomy exhibited increased cytokines, delayed liver regeneration, increased cholestasis, and hepatocyte necrosis." (PMID 33266235, 2020). "Cholestasis was induced in wild type and GPBAR1-/- mice by administration of α-naphthyl-isothiocyanate (ANIT) or 17α-ethynylestradiol." (PMID 26177448, 2015). "Previous study showed that the GPBAR1‐dependent anti‐inflammatory effects during cholestasis may occur downstream of BA‐mediated hepatocyte inflammation." (PMID 39031498, 2024). "This dichotomous function of GPBAR1 limits its use in cholestasis." (PMID 35095513, 2021). "GPBAR1 mainly regulates cholestasis in a holistic system of liver-gallbladder-gut formation." (PMID 35095513, 2021). "Considering that GPBAR1 is hardly expressed in hepatocytes but is enriched in macrophages and Kupffer cells, GPBAR1-dependent anti-inflammatory effects during cholestasis may occur downstream of BA-mediated hepatocyte inflammation." (PMID 35095513, 2021). "It is important to note that this effect is the exact opposite of what GPBAR1 needs to do in cholestasis, and the late stage of cholestasis may be the key point for the functional transformation of GPBAR1." (PMID 35095513, 2021). "Few studies have explored the combined effects of GPBAR1 and inflammasomes in cholestasis." (PMID 35095513, 2021). "However, scholars have shown that the activation of GPBAR1 activates the NLRP3 inflammasome, causing inflammation in the liver during cholestasis." (PMID 35095513, 2021). "Does the intestinal microbiota act as another channel through which GPBAR1 regulates cholestasis?" (PMID 35095513, 2021). "Moreover, existing research suggests that GPBAR1 can inhibit the progression of cholestasis by inhibiting liver inflammation." (PMID 35095513, 2021). "Whether Chinese herbal medicine also plays a role in the treatment of cholestasis partly through the activation of GPBAR1 may be an interesting line of inquiry." (PMID 35095513, 2021). "In the state of cholestasis, the activation of GPBAR1 could regulate liver inflammation, induce cholangiocyte regeneration to maintain the integrity of the biliary tree, control the hydrophobicity of the bile acid pool and promote the secretion of bile HCO3−." (PMID 35095513, 2021). "To further explore the role of GPBAR1 in cholestasis, we have then investigated whether betulinc acid triggers or exacerbates itching when administered systemically to mice rendered cholestatic by ANIT." (PMID 26177448, 2015).
cholestasis (continued). "Compared with the development of natural GPBAR1 agonists, botanical drugs that act directly on diseases may attract more attention, as traditional Chinese herbs both monotherapies and formulations, have shown favourable efficacy in mouse models of cholestasis." (PMID 35095513, 2021). "Furthermore, in the pathological state of cholestasis, BA-activated GPBAR1 may mainly affect enterohepatic circulation organs, including the liver, gallbladder and intestine." (PMID 35095513, 2021). "The protective effect of the GPBAR1 agonist on cholestasis-induced liver injury was significantly weakened in JAM-A-KO mice, and GPBAR1 affected the expression and phosphorylation of the main TJP JAM-A to regulate biliary epithelial barrier function." (PMID 35095513, 2021). "During BA overload in cholestasis, BA promoted PKCζ-dependent phosphorylation of JAM-A Ser285 via GPBAR-1 activation." (PMID 33266235, 2020). "There is no doubt that the therapeutic efficacy of targeting GPBAR1 in cholestasis has great potential and should be explored." (PMID 35095513, 2021). "Once patients with cholestasis develop CCA at a later stage, the activation of the BA receptor GPBAR1 may exacerbate the situation." (PMID 35095513, 2021). "Since GPBAR-1 is absent in hepatocytes, other cell lines likely mediate the inflammatory changes i.e., during cholestasis." (PMID 33266235, 2020). "In wild type and GPBAR1-/- mice cholestasis induced by ANIT fails to induce spontaneous itching and abrogates scratching behavior caused by intradermal administration of DCA." (PMID 26177448, 2015). "Because the relation of itching and GPBAR1 expression in cholestasis is unknown, we have next investigated if BAR502 trigger itching in a rodent model of cholestasis." (PMID 26177448, 2015). "The itching response to intradermal injection of GPBAR1 agonists desensitizes rapidly and is deactivated in models of cholestasis, explain the lack of correlation between bile acids levels and itching severity in cholestatic syndromes." (PMID 26177448, 2015).
liver disease (30 papers, 2014 to 2026). "GPBAR1 gene ablation worsened the severity of liver disease caused by ANIT, as assessed by measuring bilirubin, alkaline phosphatase and AST levels (p<0.05)." (PMID 26177448, 2015). "First, the speculation of the in vivo effects of this compound could result in the identification of new therapeutical approach to FXR mediated liver disorders in which the concomitant activation of GPBAR1 is associated to severe side effects." (PMID 26740187, 2016). "As various related studies have increased, the role of GPBAR1 in liver disease has also attracted specific attention." (PMID 35095513, 2021). "TGR5 (GPBAR1) has several cell-signaling and immunoregulatory effects within liver disease due to its presence on Kupffer cells and natural killer (NK) cells." (PMID 32432119, 2020). "In conclusion, we have demonstrated that BAR501, a UDCA derivative, endowed with robust agonistic activity on GPBAR1, exerts portal pressure-lowering effects in rodent models of portal hypertension by directly regulating the expression/activity of CSE and eNOS in LSEC." (PMID 26539823, 2015). "Previous studies have shown that in the liver CSE expression/activity is increased by Farnesoid-x-receptor (FXR) ligands but, whether GPBAR1 protects against development of endothelial dysfunction in rodent models of portal hypertension is unknown." (PMID 26539823, 2015). "BAR501, a UDCA-like GPBAR1 agonist, rescues from endothelial dysfunction in rodent models of portal hypertension by exerting genomic and non-genomic effects on CSE, eNOS and ET-1 in liver sinusoidal cells." (PMID 26539823, 2015). "In the present study we report that activation of GPBAR1 in mice administered CCL4, failed to attenuate liver fibrosis, but protected against development of portal hypertension." (PMID 26539823, 2015).
liver fibrosis (19 papers, 2015 to 2026). "In silico and pharmacological characterization of these dual modulators led to the identification of compound 2o as a first-in-class LIFR/GPBAR1 modulator that reverses liver fibrosis in vitro and in vivo." (PMID 40990291, 2025). "Furthermore, GPBAR1 appears to attenuate liver fibrosis in a diabetic mouse model." (PMID 36899928, 2023). "Gpbar1 deletion in NASH- and CCl4-induced injury mouse models led to reduced hepatic fibrosis." (PMID 36899928, 2023).
gastric cancer (15 papers, 2015 to 2025). A primary or metastatic malignant neoplasm involving the stomach. "By immunohistochemistry and RT-PCR analysis we found that expression of GPBAR1 associates with advanced gastric cancers (Stage III-IV)." (PMID 27409173, 2016). "Because DFN406 has a specific action on the receptor, we can conclude that GPBAR1 is mechanistically involved in EGF-R phosphorylation caused by TLCA in gastric cancer cells." (PMID 27409173, 2016). "GPBAR1 has been reported to be a tumor suppressor in several cancer types, including gastric cancer and colon cancer." (PMID 36755861, 2022). "In summary, we report that GPBAR1 is expressed in advanced gastric cancers and its expression correlates with markers of EMT." (PMID 27409173, 2016). "We have first investigated the expression of the two major bile acid activated receptors, FXR and GPBAR1, in surgical samples obtained from patients who underwent surgery for the treatment of gastric cancer at the University Hospital of Perugia." (PMID 27409173, 2016). "In in vitro experiments we have shown that activation of GPBAR1 in gastric cancer cells trigger the EMT and acquisition of aggressive phenotype." (PMID 27409173, 2016). "Present results highlight the potential of GPBAR1 antagonist in the management of advanced gastric cancer." (PMID 27409173, 2016). "In conclusion, we have provided evidence that advanced gastric cancer are characterized by high expression of the bile acid receptor GPBAR1 and that expression of this receptor strongly correlated with that of N-cadherin." (PMID 27409173, 2016). "In contrast, other studies demonstrate that activation of GPBAR1 reduces gastric cancer proliferation suggesting a protective role of this receptor against gastric cancer dissemination." (PMID 27409173, 2016). "Because these data suggest a role for GPBAR1 in determining a more aggressive phenotype, we have then investigated whether GPBAR1 was expressed in gastric cancer cell lines and its activation results in a migratory phenotype." (PMID 27409173, 2016). "Because GPCRs are known to regulate cell migration, proliferation, differentiation and survival and play a mechanistic role in the development and progression of several cancers, we have then investigated whether GPBAR1 exerts regulate effects on gastric cancer cell lines." (PMID 27409173, 2016). "In this study we have investigated whether GPBAR1 is involved in gastric cancer dissemination." (PMID 27409173, 2016). "Thus, we have investigated whether gastric cancer cells stimulation with an agonist of GPBAR1 results in the phosphorylation of the EGFR." (PMID 27409173, 2016). "Previous studies have reported that GPBAR1 (TGR5) in AGS cell line, and we now show that two additional gastric cancer cell lines, MKN45 and MKN74, express the gene." (PMID 27409173, 2016). "In contrast to GPBAR1, gastric cancer cells did not express FXR protein, with MKN45 cells showing ≈ 100 folds lower expression of FXR mRNA in comparison to HepG2 cells (a human hepato-carcinoma cell line used as control)." (PMID 27409173, 2016). "Thus, the NLRP3 inflammasome promotes gastric cancer and its downregulation by the activity of the aryl hydrocarbon receptor (AhR), dopamine receptor D1 (DRD1) and G protein-coupled bile acid receptor 1, (GPBAR1) may limit the occurrence of pyroptosis, thereby affecting cancer progression." (PMID 37081882, 2023).
Pruritus (12 papers, 2019 to 2025). Pruritus is an itch or a sensation that makes a person want to scratch. "We may not be able to roughly define the complex relationship between GPBAR1 and pruritus." (PMID 35095513, 2021). "Pruritus is expected to be an ADR, potentially due to the activation of cell surface bile acid receptors (GPBAR1)." (PMID 38071661, 2023).
Sepsis (12 papers, 2017 to 2025). Sepsis is defined as life-threatening organ dysfunction caused by a dysregulated host response to infection. "Hence, the G protein-coupled bile acid receptor-1 (Gpbar1 aka Takeda G protein-coupled receptor-5 [TGR5]) was downregulated in experimental sepsis." (PMID 37638006, 2023).
hepatocellular carcinoma (11 papers, 2016 to 2026). A malignant tumor that arises from hepatocytes. "Aberrant DNA methylation of GPBAR1 is identified as a potential biomarker for hepatitis B virus-associated hepatocellular carcinoma." (PMID 36755861, 2022).
nonalcoholic steatohepatitis (11 papers, 2016 to 2025). "Reduced GPBAR1 expression has been noted in non-alcoholic steatohepatitis models, where GPBAR1 inhibits NLRP3 activation and fosters macrophage M2 polarization to mitigate inflammation." (PMID 40558546, 2025).
steatosis (11 papers, 2014 to 2025). Increased lipid within the cytoplasm of cells. "Because compound 2 is a dual CysLT1R antagonist/GPBAR1 agonist and NAFLD/NASH is an orphan indication, we have decided to investigate whether this novel chemical entity is effective in protecting against the development of steatosis and fibrosis in a rodent model of NASH." (PMID 35559268, 2022).
breast carcinoma (10 papers, 2019 to 2025). "Intestinal anaerobic bacteria, such as Clostridia spp., are one of the largest producers of lithocholic acid (LCA), a secondary bile acid found to decrease breast cancer cell proliferation through the activation of the G-protein-coupled bile acid receptor 1 (TGR5)." (PMID 37566024, 2023).
cholangiocarcinoma (10 papers, 2018 to 2025). A carcinoma that arises from the intrahepatic biliary tree (intrahepatic cholangiocarcinoma) or from the junction, or adjacent to the junction, of the right and left hepatic ducts (hilar cholangiocarcinoma). "However, the characteristic of GPBAR1-mediated proliferation increases the risk of proliferation of cholangiocarcinoma in malignant transformed cholangiocytes." (PMID 35095513, 2021). "GPBAR1 is upregulated and promotes the progression of gallbladder cancer, cholangiocarcinoma, and lung cancer." (PMID 36755861, 2022). "However, GPBAR1 activation can change from beneficial to detrimental in the case of malignant transformed cholangiocytes and promote the risk of cholangiocarcinoma (CCA) proliferation." (PMID 35095513, 2021). "However, GPBAR1 promotes progression or correlates with a poor prognosis in some other cancers, including lung cancer, cholangiocarcinoma, and gallbladder cancer." (PMID 36755861, 2022).
colorectal cancer (10 papers, 2021 to 2025). A primary or metastatic malignant neoplasm that affects the colon or rectum. "Primary bile acids are endogenous ligands of several transcription factors of the nuclear hormone receptor family, and can directly cause the activation of G protein-coupled bile acid receptor 1, thereby indirectly activating NF-κB and ultimately inducing colorectal cancer." (PMID 38674835, 2024).
depression (10 papers, 2022 to 2025). "In addition to the synthetic agonists of GPBAR1, some natural agonists of GPBAR1 could also improve the cognitive function and alleviate depression." (PMID 36361829, 2022). "Intriguingly, the hippocampal CA3 pyramidal neurons’ GPBAR1 expression was reduced in the chronic restraint stress (CRS) and CSDS models of depression." (PMID 36361829, 2022).
liver cancer (10 papers, 2018 to 2024). An epithelial or non-epithelial malignant neoplasm that arises from the liver. "Furthermore, BA receptors, farnesoid X receptor (FXR), and G protein-coupled bile acid receptor 1 (TGR5) are the potential regulators for BA homeostasis and carcinogenic effects in liver cancer." (PMID 33163393, 2020).
Crohn disease (8 papers, 2011 to 2022). A gastrointestinal disorder characterized by chronic inflammation involving all layers of the intestinal wall, noncaseating granulomas affecting the intestinal wall and regional lymph nodes, and transmural fibrosis. "These include genes such as NUSAP1 and MS4A6A that are associated to glomerulonephritis, an IgA nephropathy; GPBAR1 that is highly expressed in intestinal monocytes of patients with inflamed Crohn's disease, and; SYNJ1 and PLD3 that are both associated to Parkinson's disease and Alzheimer's disease." (PMID 26338775, 2015). "Since intestinal inflammation differentially modulates ileal and colon expression of ACE2 mRNA in Crohn’s disease patients, we further investigated the mechanisms involved in the regional regulation of ACE2 and focused our attention on the bile acid receptor GPBAR1." (PMID 35406751, 2022).
Hepatitis (8 papers, 2017 to 2025). Inflammation of the liver. "Primarily through G protein-coupled bile acid receptor-1 (GPBAR1) inactivation, it promoted the secretion of the anti-inflammatory cytokine interleukin 10 (IL-10), thereby attenuating liver damage in Con A-induced hepatitis." (PMID 36293518, 2022). "Here, we have investigated whether BAR502, a non-bile acid, steroidal dual ligand for FXR and GPBAR1, reverses steato-hepatitis in mice fed a high fat diet (HFD) and fructose." (PMID 28202906, 2017).
primary biliary cholangitis (8 papers, 2016 to 2025). Primary biliary cholangitis (PBC) is a chronic and slowly progressive cholestatic liver disease of autoimmune etiology characterized by injury of the intrahepatic bile ducts that may eventually lead to liver failure. "Our investigation revealed that targeting GPBAR1 is approved for the treatment of primary biliary cirrhosis, bile acid synthesis disorders, and various other diseases." (PMID 38707907, 2024).
Cognitive impairment (7 papers, 2020 to 2025). Abnormal cognition is characterized by deficits in thinking, reasoning, or remembering. "However, the GPBAR1 expression is significantly decreased in mice with an Aβ1-42-induced cognitive impairment." (PMID 36361829, 2022). "There was no discernible difference in the GPBAR1 expression between the mouse model of the 1-Methyl-4-phenyl-1,2,3,6-tetrahydropyridine-induced motor impairments and cognitive impairment and the control group." (PMID 36361829, 2022).
inflammatory bowel disease (7 papers, 2015 to 2025). A spectrum of small and large bowel inflammatory diseases of unknown etiology. "In contrast, another bile acid receptor, the G protein-coupled bile acid receptor 1 (TGR5), has been implicated in promoting inflammation, particularly in the context of inflammatory bowel disease (IBD), a recognized risk factor for CRC." (PMID 40771692, 2025).
primary sclerosing cholangitis (7 papers, 2010 to 2026). "In 2010, sequencing of GPBAR1 in 267 patients with primary sclerosing cholangitis (PSC) rendered five non-synonymous mutations that can reduce TGR5 function, but no data on plasma lipid parameters were reported." (PMID 35011746, 2021). "TGR5, the G protein-coupled bile acid receptor 1 (GPBAR1), has been linked to inflammatory pathways as well as bile homeostasis, and could therefore be involved in primary sclerosing cholangitis (PSC) a chronic inflammatory bile duct disease." (PMID 20811628, 2010). "In addition, in a mouse model of xenobiotic (DDC)-induced sclerosing cholangitis, mice overexpressing GPBAR1 showed less liver injury while mice lacking GPBAR1 showed aggravation of inflammation and fibrosis." (PMID 27381677, 2016).
Anxiety (6 papers, 2019 to 2025). Intense feelings of nervousness, tension, or panic often arise in response to interpersonal stresses. "Reports also suggest that SBAs can facilitate the activation of thyroid hormones via the G protein-coupled bile acid receptor 1 (GPBAR1), proposing an additional pathway for their role in anxiety regulation." (PMID 39717701, 2024).